MMP9 (matrix metallopeptidase 9)
Diseases named in the same sentence as MMP9 in open-access papers (continued):
Sharing a sentence is not in itself a finding about the gene and the disease.
neuroblastoma (continued). "The efficiency of the selected PCR primers for MMP-9 was established by amplification of the appropriate PCR product in N2a neuroblastoma cells and astrocytes (not shown)." (PMID 20011518, 2009). "In neuroblastoma cells, overexpression of SPARC can inhibit endothelial cell formation and cell proliferation, including induction of programmed cell death and the inhibition of angiogenic factors expression, such as FGF VEGF, PDGF, and MMP-9 in endothelial cells." (PMID 29262657, 2017). "Interestingly, omentin-1 may influence the growth and aggressiveness of neuroblastoma cells through the upregulation of the N-myc downstream regulated gene 2, which attenuates the expression of vascular endothelial growth factor (VEGF) and matrix metalloproteinase 9 (MMP-9)." (PMID 34827610, 2021). "To investigate the cellular distribution of MMP-9 in nontreated and TWEAK-treated endothelial cells, we used an antibody for MMP-9 whose specificity had been previously validated on neuroblastoma N2a cells transfected with MMP-9-GFP-constructs." (PMID 23320797, 2013).
thyroid cancer (53 papers, 2010 to 2026). "Overexpression of the zinc-dependent metalloproteinase MMP9 has been previously associated with invasion of follicular ML-1 thyroid cancer cells." (PMID 32603365, 2020). "We investigated the diagnostic and prognostic value of the MMP9/miR-145 ratio in thyroid cancer, hypothesizing it may overcome inter-patient heterogeneity and serve as a versatile biomarker regardless of genetic mutations or autoimmune status." (PMID 38001954, 2023). "We have previously shown that Neutrophil Gelatinase-Associated Lipocalin (NGAL) is strongly expressed in thyroid carcinomas, especially of anaplastic type, where it protects neoplastic cells from serum deprivation-induced apoptosis and enhances tumor invasivity by regulating MMP-9 activity." (PMID 30112105, 2018). "Among them, MMP9 has been shown to promote thyroid cancer incidence and progression in a large number of literatures, which is consistent with our findings." (PMID 40963858, 2025). "Further large-scale validation and protocol standardization can facilitate clinical translation of the MMP9/miR-145 ratio to guide personalized thyroid cancer management." (PMID 38001954, 2023). "This review describes MMP-9 as a tumor marker for thyroid cancer, for this protein is involved in multiple aspects of the progression of the tumor." (PMID 37175113, 2023). "The inhibition of MMP-9 exhibits favorable abilities for treatment in multiple disorders, including thyroid cancer as well." (PMID 37175113, 2023). "As a consequence, ginsenoside compounds can be considered as MMP-9 inhibitors applied to treat different kinds of disorders, including thyroid cancer." (PMID 37175113, 2023). "The review summarizes and enumerates MMP-9 inhibitors or MMP-9 inhibitory molecules applied to thyroid cancer and other disorders." (PMID 37175113, 2023). "Under the background of thyroid cancer, high levels of MMP-9 promote the EMT process, bound up with the invasion, migration, metastasis, and apoptosis of thyroid cancer cells." (PMID 37175113, 2023). "In a word, discovering and designing MMP-9 inhibitors provide great therapeutic effects and promising clinical values in various types of thyroid carcinoma." (PMID 37175113, 2023). "It has been proved that MMP-9 expression elevates in multiple pathological conditions, including thyroid carcinoma." (PMID 37175113, 2023). "Some researchers have analyzed the clinical significance of MMP-9 levels to predict the prognosis of thyroid carcinoma in longitudinal studies." (PMID 37175113, 2023). "CircRNA DOCK1 not only becomes enriched in tumor tissues but also induces the accumulation of MMP-9, contributing to thyroid carcinoma." (PMID 37175113, 2023). "Our findings indicate the potential value of an immune-related risk score composed of MMP9 and SDC2 for predicting dedifferentiation and survival in thyroid carcinoma." (PMID 33892730, 2021). "They found that the levels of VEGF and MMP-9 in BCPAP thyroid cancer cells expressing PTCSC3 were significantly downregulated to inhibit invasion and metastasis." (PMID 32596158, 2020). "In particular, previous studies have reported an increase in MMP-2 and MMP-9’s mRNA and protein levels in a variety of thyroid cancer cells." (PMID 30509240, 2018). "In the present study, we have investigated the expression, secretion and activity of MMP2 and MMP9 in thyroid cancer C643 cells where S1P inhibits invasion." (PMID 29734379, 2018). "Previous studies show that increased expression and activity of MMP2 and MMP9 in thyroid cancer cells promotes invasion." (PMID 29734379, 2018). "Recently, we have shown that blocking MMP2 and MMP9 attenuated S1P-evoked follicular ML-1 thyroid cancer cell invasion." (PMID 29734379, 2018). "MMP2 and MMP9 are gelatinases which use collagen IV as their main substrate and regulate thyroid cancer cell invasion." (PMID 29734379, 2018). "It has been demonstrated that MMP9 play important roles in the development and progression of thyroid cancer." (PMID 29632659, 2018).
thyroid cancer (continued). "Among the MMP family members, an increased expression and activity of both MMP2 and MMP9, which use type IV collagen as their substrate, has been reported to correlate with enhanced invasion of thyroid cancer cells." (PMID 29137300, 2017). "Many MMP family members, such as MMP2, MMP7, MMP9, MMP11, and MMP13, have been implicated to be associated with the development and progression of thyroid cancer." (PMID 28709407, 2017). "This is in contrast with previous reports, where abundant expression of MMP-9 correlated significantly with invasion and metastasis of thyroid carcinomas." (PMID 24778099, 2014). "These MMPs are significant in that they are regulated by NF-κB (MMP-9) and expressed ubiquitously in thyroid cancer cell lines (MMP-13)." (PMID 20492683, 2010). "Inhibition of MMP-9 suppresses the occurrence of EMT and consequently retards the tumor progression, increases the survival time, and improves the survival quality of patients, which further proves the therapeutic abilities of MMP-9 inhibitors used in thyroid cancer." (PMID 37175113, 2023). "The expression of MMP-9 increases in various pathological processes, including thyroid cancer." (PMID 37175113, 2023). "In addition to chemical molecules, there are some other approaches inhibiting the expression of MMP-9 and assisting in the treatment of thyroid carcinoma." (PMID 37175113, 2023). "Therefore MMP-9, showing high malignant potential in thyroid carcinoma, can be considered as a kind of biomarker assisting in diagnosing the pathological type of tumors, assessing the metastatic status, and evaluating the therapeutic effects of the operation." (PMID 37175113, 2023). "MMP-9 expression is found to be greatly upregulated in thyroid carcinomas." (PMID 34684168, 2021). "MMP-9 could be detected not only in thyroid tissue but also in peripheral blood in patients with normal thyroid, benign pathologies, and thyroid cancer." (PMID 34684168, 2021). "In this paper, we explored the effect of MMP-9 on the development of thyroid cancer (TC) and verified that MMP-9 could promote the EMT process of TC induced by TGF-β1." (PMID 32698816, 2020). "Among the matrix metalloproteinases, MMP-9 has an important role not only in extracellular matrix degradation during tissue remodeling, but also in pathological processes such as invasion and metastasis of tumor cells and overexpresses in thyroid cancer cells." (PMID 32760219, 2020). "Various studies showed that BTG1 overexpression suppressed proliferation, migration and invasion, and induced apoptosis and cell cycle arrest of lung, kidney, breast, esophageal, hepatocellular, nasopharyngeal, and thyroid cancers with Cyclin D1, Bcl-2, and MMP-9 hypoexpression." (PMID 33330092, 2020). "The purpose of this study is to explore the role and mechanism of MMP-9 in the EMT process of thyroid cancer (TC), so as to provide a basis for clinical exploration of invasion and metastasis process of TC, looking for biological markers of tumor metastasis and molecular intervention therapy." (PMID 32698816, 2020). "Interestingly, growth factors are demonstrated to stimulate MMP-9 activation in head and neck squamous cell carcinoma and elevated levels of MMPs have been demonstrated in thyroid carcinoma." (PMID 21267453, 2011). "Interestingly, in thyroid cancer, MMP-9 may induce tumor invasion by promoting epithelial–mesenchymal transition, thus altering the migration and invasion ability of cancer cells." (PMID 40869267, 2025). "MMP-9 inhibitory molecules also assist in treating thyroid tumors by suppressing the proliferation, invasion, migration, metastasis, viability, adhesion, motility, epithelial-mesenchymal transition (EMT), and other risk factors of different thyroid cancer cells." (PMID 37175113, 2023).
thyroid cancer (continued). "Proteomic studies on PTC tissue from humans have suggested NTRK1, metalloproteinases (MMP-1, MMP-9 and MMP-13) and Cathepsins (-W and -X), NF-KB and other apoptosis associated proteins as radiation-induced PTC biomarkers, together with SPANXA as an important protein for thyroid cancer development." (PMID 33382739, 2020). "However, the role of MMP2 and MMP9 in S1P-evoked inhibition of invasion of thyroid cancer cells remained unknown." (PMID 29734379, 2018). "It promotes intracellular iron capture and the formation of complexes with matrix metalloproteinase 9 (MMP9) with pro-malignant potential in breast, esophagus, stomach, brain, and thyroid cancer." (PMID 38542201, 2024). "Matrix metalloproteinase 9 (MMP9) and microRNA-145 (miR-145) have emerged as essential biomarkers in thyroid cancer progression and metastasis." (PMID 38001954, 2023). "When applied to the treatment of thyroid cancer, celecoxib decreases the protein and mRNA levels of COX-2, MMP-9, and VEGF in human medullary thyroid cancer TT cells in vitro and in the nude mice model of human medullary thyroid cancer in vivo." (PMID 37175113, 2023). "The review focuses on the role of MMP-9 as a biomarker and MMP-9 inhibition as a treatment method in various diseases, taking thyroid carcinoma as an instance." (PMID 37175113, 2023). "Evidence have shown that linc00312 inhibited cell growth and migration of thyroid cancer cells through suppressing the PI3K/Akt and MMP-9." (PMID 34336850, 2021). "Recently, we have reported that S1P induces secretion and activity of MMP2 and MMP9 through S1PR1,3, and that these MMPs are important for the S1P-evoked invasion of thyroid cancer ML-1 cells." (PMID 29734379, 2018). "Compared with the two other thyroid cancer cell lines (SW579 and TT), higher MMP9 protein and mRNA expression were observed in THY28 cells." (PMID 27811013, 2016). "As predicted, positive MMP-9 and TIMP-2 immunoreactivity was detectable in the cytoplasm of thyroid cancer cells, but rarely in stromal cells or surrounding healthy thyroid tissue." (PMID 24527080, 2014). "In addition, we have recently shown that estrogen enhances thyroid cancer cell proliferation and metastasis associated events such as migration, adhesion and invasion, at least partly by induction and activation of essential proteolytic enzymes, mainly matrix metalloproteinases-2 (MMP-2) and MMP-9." (PMID 22548798, 2012). "To investigate the mechanism by which NF-κB regulates thyroid cancer cell invasion, we performed quantitative RT-PCR to examine the NF-κB-dependent regulation of the matrix metalloproteinase (MMP) -2, MMP-9, and MMP-13." (PMID 20492683, 2010). "TIMP1, a secreted protein best known for its inhibitory effects on matrix metalloproteinase 9 (MMP9), has been documented as overexpressed in multiple malignancies including lung, prostate, and thyroid cancers —a finding consistent with our observations in LUAD." (PMID 41187171, 2025). "In the present study, the results demonstrated that overexpression of LKB1 could inhibit migration and invasion of thyroid cancer TPC-1 and BCPAP cells, and downregulate the expressions of MMP2 and MMP9." (PMID 35912012, 2022). "Indeed, in the SW1736 thyroid cancer cell line, IL-17B-dependent stimulation of IL-17RB induces ERK1/2 activation and increases expression of the matrix metalloproteinase MMP-9 expression, a key mediator of tumor invasion and metastasis formation." (PMID 32373132, 2020). "Deletion of RET in thyroid carcinomas has been shown to reduce the production of MMP2 and MMP9." (PMID 33020210, 2020). "Moreover, in thyroid cancer it increased from 33% in stage III to 75% in stage IVA, indicating that MMP-9 was expressed more in advanced stages of malignant diseases." (PMID 30509240, 2018). "In addition, LKB1 overexpression could inhibit migration and invasion, downregulate MMP2 and MMP9 expressions, and reverse EMT in thyroid cancer cells." (PMID 35912012, 2022).
thyroid cancer (continued). "Apart from natural MMP-9 inhibitors, there are some non-natural molecules possessing MMP-9 inhibitory abilities in thyroid cancer cells, although they are not mainly used in the treatment of thyroid carcinoma." (PMID 37175113, 2023). "The expression of uPA, MMP2, and MMP9 was negative in almost all NT and AG, while the ratios of positive uPA, MMP2, and MMP9 expression were high in thyroid cancer specimens." (PMID 29137300, 2017).
diabetic nephropathy (52 papers, 2009 to 2025). "A study on MMP9 promoter methylation suggested that serum circulating levels were inversely associated with methylation level in Diabetic nephropathy patients." (PMID 35246549, 2022). "Increased levels of MMP-9 were found to be associated with higher albuminuria levels in a number of kidney diseases in humans, namely glomerulonephritis and diabetic nephropathy." (PMID 34439968, 2021). "In the present study, we also found that the appearance of MMP-9 positive PECs on the glomerular tuft was frequently associated with the loss of podocyte marker proteins in affected glomeruli in advanced stages of diabetic nephropathy." (PMID 25849723, 2015). "Taken together, we have demonstrated that an up-regulation of MMP-9 in activated parietal epithelium is associated with a loss of adjacent podocytes in progressive diabetic nephropathy." (PMID 25849723, 2015). "A study of meta-analysis has revealed that mutation of the promoter of MMP-9 gene decreases the risk of diabetic nephropathy." (PMID 26692905, 2015). "In the same Indian studies, another genetic variant rs17576 in the MMP9 gene was significantly associated with diabetic nephropathy with a pooled OR of 1.91 (95% CI 1.54-2.38)." (PMID 25280384, 2014). "The CCL2, IL8, CCR5 and MMP9 polymorphisms were found to be associated with the risk of diabetic nephropathy." (PMID 19357773, 2009). "Nevertheless, both MMP-9 and IL-6 have been associated with pathogenesis of diabetic nephropathy." (PMID 27101382, 2016). "The drop in kidney levels of miR-451-5p and miR-16 could lead to unchecked increased expression of their target IL-6 and MMP-9 levels which are associated with the pathogenesis of diabetes nephropathy." (PMID 27101382, 2016). "The MMP9-1562 C/T genotype was significantly associated with the risk of diabetic nephropathy after stratification by specific type of microvascular complication (CT + TT vs. CC: OR = 0.42, 95% CI = 0.26–0.69, p = 0.0006; TT vs. CC + CT: OR = 0.37, 95% CI = 0.19–0.76, p = 0.006)." (PMID 26184271, 2015). "The key finding of our study was that polymorphisms in IL8, CCL2, CCR5, and MMP9 genes were associated with increased risk of nephropathy in Asian Indian type 2 diabetics and co-occurrence of specific risk genotypes of these genes conferred several fold greater risk of diabetic nephropathy." (PMID 19357773, 2009). "There are also controversies about the level and enzymatic activity of MMP-9 in patients with systemic lupus erythematosus and diabetic kidney disease." (PMID 41341833, 2025). "An experimental study found the development of kidney diseases such as hypertensive glomerulosclerosis and diabetic nephropathy to have a correlation with the downregulation of MMP9." (PMID 39492771, 2025). "Increased concentrations of MMP-9 were found in human kidney tissue in different diseases, such as in ischemic lesions or diabetic nephropathy." (PMID 38136813, 2023). "MMP-2 and MMP-9 are two of the proteinases that have been widely studied in human diabetic kidney disease." (PMID 35629404, 2022). "This is the first study that assessed associations of MMP-9 and TIMP-1 with long-term microvascular complications in type 1 diabetes, primary diabetic neuropathy, and diabetic nephropathy." (PMID 33775157, 2021). "Other studies have shown that DZHSI can inhibitthe expression of MMP-9 and reduce the deposition of the mesangial matrix, thereby blocking the occurrence and development of diabetic nephropathy." (PMID 34539390, 2021). "Metalloproteinase-9 (MMP-9) has been associated with matrix turnover, and Neutrophil gelatinase associated lipocalin (NGAL) is a marker of tubular injury in diabetic nephropathy." (PMID 33775157, 2021). "In 24-h urine collection, MMP-8 and MMP-9 activity has been shown to be elevated in accordance with the stage of diabetic nephropathy in T2DM patients, compared to healthy age-matched controls." (PMID 33362965, 2020).